RNU6-842P (RNA, U6 small nuclear 842, pseudogene)
Gene: Small nuclear RNA gene on chromosome 8 (13,044,350 to 13,044,456, forward strand). Ensembl gene ENSG00000206996.
Homologues: Orthologues: chimpanzee U6 (97% identical), rat U6 (95% identical), mouse Gm24928 (88% identical), guinea pig U6 (87% identical). Paralogues in human: RNU6-12P (94% identical), RNU6-13P (94% identical), RNU6-25P (94% identical), RNU6-32P (94% identical), RNU6-33P (94% identical), RNU6-41P (94% identical), RNU6-1 (93% identical), RNU6-17P (93% identical), RNU6-18P (93% identical), RNU6-2 (93% identical), RNU6-3P (93% identical), RNU6-48P (93% identical), and 1287 more.